BCL2 (BCL2 apoptosis regulator)
Diseases named in the same sentence as BCL2 in open-access papers (continued):
Sharing a sentence is not in itself a finding about the gene and the disease.
tumor (continued). "In our case, immunohistochemical staining was performed, showing positive expression of C10 and Bcl-2 in tumor cells and negative for CEA and EMA, confirming the diagnosis of conjunctival BCC." (PMID 39027412, 2024). "Studies have shown that rosmarinic acid blocks the G2/S cycle in pancreatic carcinoma cells by adjusting the communication of cyclin E, BAX and Bcl-2; inhibits the migration and invasion of pancreatic cancer cells through E-cadherin and Matrix metallopeptidase 9 (MMP-9); and inhibits tumor growth." (PMID 38675663, 2024). "In contrast, Navitoclax and Venetoclax only partially reduced neutrophil survival at the highest dose (100 nM) (Fig. EV3B), showing that Bcl-xL but not Bcl-2 mediates neutrophil survival in tumor supernatant conditions." (PMID 38177532, 2024). "In mice, compared with NSCLC mice, the tumor volume and weight of the IFN-γ group were increased, the expression of CD163, CD206, IDO1, Ki-67 and Bcl-2 in tumor tissue was upregulated, the expression of Bax and C-caspase 3 was downregulated, and apoptosis was reduced." (PMID 38254043, 2024). "The results showed that high BCL-2 expression was significantly associated with longer overall survival (OS) and relapse-free survival (RFS), independent of tumor size and lymph node status." (PMID 39685591, 2024). "The binding of IL-17 to IL-17R on tumor cells activates downstream molecules, including transcription factors (NF-κB, STAT, and AP-1), kinases (MAPK and HER1), matrix metalloproteinases (MMPs), and anti-apoptotic proteins (Akt, Erk, mTOR, Bcl-2, and Bax)." (PMID 39205642, 2024). "Therefore, an in-depth study of the mechanism of interaction of the BCL2 protein with other factors may help elucidate the molecular mechanism of apoptosis regulation and provide a theoretical basis for the development of more effective tumour therapeutic regimens." (PMID 38915053, 2024). "Two doses of carvacrol nanoemulsion (CANE, and 100 mg/Kg) over 4 weeks in an athymic nude mouse model significantly reduced tumour growth and tumour weight by 34.2% and 62.1%, respectively, and increased the expression of p‐JNK, Bax, Bcl2, Cyt C, Cas‐3, Cas‐9 and β‐actin in lung tissue." (PMID 37697969, 2023). "Depletion of the NCOA3-p300-NF-κB components or blockage of NCOA3 function with inhibitors (gossypol and bufalin) in ER-positive cells suppressed BCL2, BCL2A1, BCL2L2, and MCL1 expression, while also decreasing cell viability, colony formation, cell invasion, and tumor growth." (PMID 36853387, 2023). "We also harvested a small fraction of co-cultured tumor cells for Western blot and found that ISG15-overexpressed cells showed higher expression of active caspase-3 and Bax proteins and lower expression of Bcl-2 than ISG15-depleted cells." (PMID 37217923, 2023). "However, a dramatic suppression of BCL2 was observed after the combined treatment of PF and LAQ, which inhibits anti-apoptotic protein expression to promote apoptosis in tumor cells." (PMID 37686467, 2023). "For colorectal cancer SW480 cells, clofibrate significantly inhibits tumor proliferation and sensitizes SW480 cells to chemotherapy drugs in a PPARα-dependent manner, thereby inducing anti-apoptotic Bcl2 protein degradation and promoting autophagy in tumor cells." (PMID 37251321, 2023). "Selenium plays an important role in increasing the expression levels of Caspase-1, Caspase-3, Caspase-8, and Caspase-9 and decreasing the expression levels of Bcl-2 and LC3, which promote the development of cellular pyroptosis and apoptosis and increase the rate of tumor cell death." (PMID 37994159, 2023). "PE was able to enhance the antioxidant capacity of H22 tumor-bearing mice bodies so that the SOD level and pro-apoptotic protein Bax expression in tumor tissues were obviously upregulated, while the MDA level and the expression of the inhibitor apoptotic protein Bcl-2 were downregulated." (PMID 38202798, 2023).
tumor (continued). "In these studies, suggest that miR-224-5p plays a significant role in the occurrence in HCC samples compared to adjacent tumor tissue samples, which is consistent with our findings that miR-224-5P was four times more abundant in HCC tissues with highly represented BCL2, MTOR, and GSK3B genes." (PMID 37168369, 2023). "Furthermore, inhibition of the NMT1/VILIP3/NFκB/Bcl-2 regulatory axis was observed in the desloratadine-treated PDX#1 and PDX#2 tumor xenografts, as indicated by Western blot." (PMID 36617552, 2023). "The expression of pro-apoptotic proteins FasL and Bax, as well as anti-apoptotic protein Bcl-2, was studied in rats under various treatment conditions; tumor-free rats served as the negative control." (PMID 36877301, 2023). "Negative expression of Bcl-2 was found in tumors, and positive expression (65%) was found in adjacent non-tumor tissue, mainly in immune cells." (PMID 37186587, 2023). "Our results showed a higher level of Bax and down-regulation of Bcl-2 in nanogold conjugated with heat-killed yeast than heat-killed yeast alone in comparison to the non-treated DMBA-induced tumor group." (PMID 36877301, 2023). "In some cases, such as the highly mutated BCL2 and BCL6, individual TFA-BT NCVs are generally not recurrent but affect the binding of the same TFs at different positions in the promoter across tumor samples." (PMID 36808133, 2023). "This indicates that Regorafenib-induced upregulation of Bcl-2 is a tumor-cell autonomous resistance mechanism which is not dependent on non-autonomous TAM-derived PGE2 secretion." (PMID 37620408, 2023). "Recently, a team exploited a unique CAR construct by integrating Bcl-2 into CAR-T cells and found that this strategy could enhance CAR-T cells’ proliferation, thereby enhancing the anti-tumor activity in xenografted lymphoma mice and prolonging their lifespan." (PMID 36701037, 2023). "Furthermore, the increased protein level of VEGFC and BCL2 as well as reduced cell apoptosis caused by depletion of UTX could be rescued by ectopic expression of EMP1, suggesting that EMP1 is a significant effector gene mediating the tumor-suppressing function of UTX in CRC." (PMID 37679762, 2023). "Furthermore, western blot detected several apoptosis-related proteins (Bax and Bcl-2), EMT pathway biomarkers related to tumor transition (E-cadherin and Vimentin) and cell cycle protein (CyclinD1)." (PMID 36854894, 2023). "The results showed that BCL2, APC, TCF, WNT, AXIN, and CTNNB1 (p < 0.05) were significantly higher expressed in tumor tissues compared to adjacent healthy tissues, and BAX was higher in control tissues than tumor tissues (p < 0.05)." (PMID 37644520, 2023). "Therefore, to further confirm our findings on cell survival and death in tumor tissues of PDX mice, we performed immunoblot analyses of phospho-BAD and Bcl-2 in tumors of in p402 mAb- and p40 mAb-treated PDX mice." (PMID 38136341, 2023).
tumor (continued). "Our present data supported the function of RNU12 in inhabiting GC tumor progression through suppressing the cell growth, migration, invasion, as well as the proliferative ability expression with CCND1, PCNA, N-cadherin, E-cadherin, Vimentin and BCL-2." (PMID 37160927, 2023). "Second, due to the lack of detailed information on the patients, this study did not analyze the associations between BAX, BCL2 and c-MYC polymorphisms and gene expression and clinical features, such as tumor size and sensitivity to treatment." (PMID 38003498, 2023). "A comprehensive genomic profiling on tumor paraffin-embedded tissue samples was performed in 3 out of 4 patients and no alterations of BCL-2 gene status was detected." (PMID 37935707, 2023). "They promote non-regulatory CD4 + and CD8 + T cell survival, maintain anti-apoptotic proteins BCL-XL, BCL-2 and BFL1 expression, increase cytokine production, enhance tumor-specific T cell immune responses, and increase tumor-specific memory T cell production after antigen challenge." (PMID 37462769, 2023). "In addition, RT-qPCR and immunohistochemical staining also showed that celastrol administration downregulated Claspin, Bcl-2, METTL3, and YTHDF3 in the xenograft tumor tissues." (PMID 38110764, 2023). "The expression of the anti-apoptotic BCL-2 gene in the CIMV-TRAIL group remained unchanged, while the mRNA level of the pro-apoptotic BAX gene was increased by 1.4 times, which indicated apoptosis activation in the tumor tissue." (PMID 36661524, 2023). "The expression of BCL-2 has been reported to have clinical importance in primary BC where it positively correlates with prognostic factors such as ER/PR expression, HER2 negativity, slow proliferation, and low tumor grade." (PMID 36574653, 2023). "The angiogenic potential of bcl2 is not well known, nor is the way in which tumor cells with excessive bcl2 expression affect VEGF production." (PMID 36766867, 2023). "It has been shown in tumor cells that ROS promote the transport of HMGB1 from the nucleus to the cytoplasm, while cytoplasmic HMGB1 interacts with Beclin-1, which, in turn, is released from the Beclin-1/Bcl-2 complex and induces autophagy." (PMID 37158301, 2023). "One of the mechanisms might be the decrease in Bcl-2 expression, as it was shown that PGE2 can activate Bcl-2 expression; thus, by inhibiting COX-2, PGE2 is decreased, and thus Bcl-2 will also decrease, leading to tumor regression." (PMID 37373544, 2023). "As a tumor suppressor, miR-34a also participates in the therapy resistance of progressive NB since it targets crucial players of therapy resistance including N-MYC, E2F3, BCl2, CCND1, and CDK6." (PMID 36874032, 2023). "Moreover, in the rNDV‐TRAIL group, the activation levels of Bax/Bcl‐2 ratio, Cytochrome C, and caspase 9 of the intrinsic signaling pathway were increased compared to the rNDV group in both HCT116 and HT‐29 tumor tissues." (PMID 37843231, 2023). "Bcl-2 is a STAT3-regulated downstream protein that is essential for preventing pro-apoptotic signaling pathways and fostering carcinogenesis, while Bax is the initiator of apoptosis in tumor cells, albeit with reduced levels." (PMID 38202610, 2023). "The pivotal role of STAT3 in tumor development stems from its capacity to regulate the transcription of genes involved in various key processes, such as the cell cycle (CCND1, CCNE1), metabolism (OCT1, HIF1A), and cell survival (BCL2, BCLXL, and HSP70)." (PMID 37474926, 2023). "IHC studies revealed that the tumor cells expressed CD20, BCL2, and BCL6." (PMID 36342081, 2023).
tumor (continued). "Second, AIFCM can also reverse multidrug resistance by regulating the expression of ABC transporters and multiple signaling pathways such as Bcl-2, NF-κB, and PI3K, thus sensitizing the tumor to chemotherapeutic drugs, reducing the side effects, and improving the efficacy of chemotherapy." (PMID 37497002, 2023). "Collectively, Bcl-2 BH4 domain selective antagonists may provide a potential therapeutic strategy for angiogenesis and serve as novel anti-tumor therapeutic drugs." (PMID 37237269, 2023). "Xenograft models of ACC-I were responsive to PRMT5 inhibition with a block of tumour growth; AL101 determined tumour regression in NOTCH activated ACC-I models and further synergic activity was observed when used in combination with BCL2 inhibitor or palbociclib." (PMID 37795454, 2023). "Our study further analyzed the signal pathways that may performed in the tumorigenesis and revealed the sensitivity of PCSK9 correlated with anti-tumor drugs in tumor treatment and their corresponding targets, such as PAK1, BCL2 and MDM2." (PMID 37860186, 2023). "In contrast to WT mice, intratumoral Treg cells from 9464D tumor bearing vav-BCL-2 mice were not depleted after low-dose CPM administration." (PMID 36097618, 2022). "Moreover, associations between the expression of several genes or proteins and the benefits of paclitaxel, such as CCND1, ABCB1, BCL-2, and SPARC in different tumor types, have been reported in multiple studies 25–29." (PMID 35595817, 2022). "Positive correlations were found between CD20 and Bcl2 (r=0.695, p=0.001), CD3 (r=0.598, p=0.550), CD4 (r=0.550, p=0.012), CD8 (r=0.567, p=0.009) and Ki67 (r=0.558, p=0.011), which confirm our previous findings in the tumor areas." (PMID 36685537, 2022). "In analogy to BCL2 knockout, venetoclax alone did not alter tumor growth, whereas the combination of venetoclax plus chemotherapy clearly decreased tumor load, indicating the potential of venetoclax to overcome treatment resistance to polychemotherapy." (PMID 36333584, 2022). "The expressions of AGK, BCL-2 and FOXO1 were evaluated in tumor tissues of DLBCL patients." (PMID 35910796, 2022). "As for the case of miRNA expression, the expression of H19, MALAT1 and BCL2 did not correlate in a statistically significant way with smoking status or tumor stage." (PMID 35723379, 2022). "Having a similar IC50 value with a clinically available Bcl-2 inhibitor ABT-199, BAU-243 demonstrated a remarkable anti-proliferative effect on the cancer sub-population that is considered a true representative of tumor-initiating GBM stem-like cells." (PMID 36309485, 2022). "Histologically, a cellular tumor comprising malignant oval to spindle cells with necrosis was observed, which was positive for Bcl-2, CD99, and FLI-1, but negative for pan-cytokeratin, STAT6, and CD34." (PMID 36033527, 2022). "TAX promoted the expression of the pro-apoptotic molecules such as Bax, Caspase-3, Caspase-9, Cyt-C and inhibited the expression of the anti-apoptosis molecules such as Bcl-2 and PARP1, indicating that TAX efficiently induced apoptosis in tumor cells in mRNA or protein levels." (PMID 36230568, 2022).
tumor (continued). "It is reported that BCL-2 proteins' expression is not sensitive to paclitaxel due to tumor genetic or epigenetic regulation, which inhibits PCD and renders the cancer cell to survive in response to PTX." (PMID 35509628, 2022). "Tumour cells were stained strongly with VIM, EGFR, and Bcl-2." (PMID 35906487, 2022). "In contrast, BCL2 and CD163 had low expressions in the tumor groups in all databases." (PMID 36551651, 2022). "Meanwhile, compared with the Model group, 3-MA reduced the expression of Bcl-2 in tumor-bearing mice, but there was no statistical difference; while 3-MA remarkably increased the expression of Bcl-xl, which was the same as that of the YFSJ group." (PMID 35645820, 2022). "By controlling the BCL2, BAX, cleaved caspase-3, MMP-2, and MMP-9 pathways, the results showed the potential of brusatol delivered by plCSA-modified NPs as a chemotherapeutic agent for the targeted therapy of tumours." (PMID 36559281, 2022). "In addition, we found that the anti-tumor effect is mediated through modulation of the CDK4/Cyclin D/RB/E2F and Caspase/Bcl-2 signal pathways." (PMID 35686110, 2022). "Notably, miR-148a is a member of the miR-148/152 family, and acts as a tumor suppressor in a variety of human solid tumors and participates in biological functions by targeting mature mRNAs, including WNT-1, Bcl-2, and KLF6." (PMID 35892859, 2022). "In this report, we evaluated the anti-tumor effect of ASP1235 in combination with venetoclax or venetoclax plus azacitidine for THP-1 cells, which are AML-derived cells expressing both FLT3 and Bcl-2." (PMID 36537913, 2022). "This transcription factor activates genes encoding the production of inflammatory cytokines and some proteins with known tumor-promoting effects such as COX2 or angiogenic factors; it is also a known promoter of survival via the induction of anti-apoptotic genes (Bcl-2)." (PMID 36361889, 2022). "In addition, the expressions of genes involved in tumor suppression (PTEN), cell growth inhibition (AURKA), and apoptosis (BIM and Bcl-2) have been measured in cells exposed to OEO." (PMID 36678556, 2022). "Targeting MDM2/TPSO (translocator protein), MDM2/PKC (protein kinase C), MDM2/NF-kB (nuclear factor-kappa B), MDM2/Bcl-2 (B-cell lymphoma-2) and MDM2/NFAT1 (nuclear factor of activated T-cells 1) had good anti-tumor activity and had the potential to reduce the adverse reactions of MDM2 inhibitors." (PMID 35831864, 2022). "FL with a predominantly diffuse growth pattern frequently occurs as a large tumour in the inguinal region and is associated with CD23 expression, an absence of IGH::BCL2 fusion, and frequent STAT6 mutations along with 1p36 deletion or TNFRSF14 mutation." (PMID 35732829, 2022). "Moreover, we observe a multitude of structural variations (SVs) in these sites, most notably deletions, inversions or tandem duplications at well-described PCa SV loci like tumor suppressors SPOPL at chr2q and DCC/BCL2 at chr18q." (PMID 36450752, 2022). "In the CDDP treatment group, Bcl-2 protein expression significantly (p < 0.05) decreased by 43% compared with the tumor group, but this increase was not significant (p > 0.05) when compared with the RTP-H treatment group." (PMID 35269987, 2022). "We found that CD8-GNLY effector T cells in high tumor infiltration group displayed increasing level of the serine/threonine kinase PIM family (PIM2 and PIM3), NR4A2/3, KLF4/6, BCL2, GPR183 and COTL1 compared to the ones from HD and low tumor infiltration group." (PMID 36532059, 2022). "In the present study, BDMC significantly inhibited the tumor growth of GBM 8401 xenograft mice in vivo via upregulating the expression of BAX (pro-apoptotic factor) and caspase-3 and downregulating the expression of Bcl-2 (anti-apoptotic factor) and XIAP in tumor tissues." (PMID 35008959, 2022).